GCG (glucagon)
Diseases named in the same sentence as GCG in open-access papers (continued):
Sharing a sentence is not in itself a finding about the gene and the disease.
tumor (continued). "To clarify the role of glucagon and its clinical relevance in CRC, we compared glucagon expression levels in tumor and normal tissues in 82 clinical samples of patients with CRC." (PMID 38072640, 2024). "As expected, the tumor cells tended to show lower expression of differentiation genes such as enterocyte markers (CA1, CA2, and CLCA1) and endocrine cell markers (PYY and GCG)." (PMID 35974387, 2022). "Paradoxically, GCG expression in COADREAD was found correlated with worse prognosis, but also higher expression was also correlated with a more hyperinflammatory tumor immune microenvironment, suggestive of tumor immunosuppression." (PMID 35340411, 2022). "In patients with PDAC and diabetes, increased serum glucagon, somatostatin and islet amyloid polypeptide (IAPP) levels were found to revert to normal following tumour resection, indicating an influence of tumour cells on the profiles of these hormones." (PMID 34680372, 2021). "Based on H & E and insulin and glucagon immunoreactivities, MPM mice exhibited the same multi-step tumor progression from hyperplastic islets to one tumor to more tumors as observed in the MPR mice." (PMID 31160716, 2020). "In the present series, the tumor cells were positive for at least one of pan-neuroendocrine markers including chromogran, synaptophysin, neuron-specific enolase, CD56, and glucagon." (PMID 27956948, 2009). "Immunohistochemically, tumor cells were positive for at least one of pan-neuroendocrine markers including chromogranin, synaptophysin, neuron-specific enolase, CD56, and glucagon." (PMID 27956948, 2009). "Canonical EEC markers and hormone genes (e.g., GCG and PYY) were likewise reduced in tumor tissue." (PMID 41303610, 2025). "GCGR‐KD tumors showed no changes in tumor growth rate or weight; however, the tumor was not further inhibited on treatment with 5‐FU plus glucagon, compared to 5‐FU treatment alone." (PMID 38072640, 2024). "Unexpectedly, glucagon did not promote colorectal cell proliferation, although western blotting revealed glucagon receptor expression in tumor cells." (PMID 38072640, 2024). "Cell viability assay revealed that the number of tumor cells decreased on combining 5‐FU with GCG@LFA compared to those with GCG+5‐FU, although no significant changes were observed with GCG@LFA compared to those with glucagon treatment alone." (PMID 38072640, 2024). "In previous publications, we tried to explain the metabolic rewiring of tumor cells by considering that tumor cells respond to both anabolic insulin and to catabolic glucagon, since enzymes such as PK and PDH remain phosphorylated, as for glucagon-mediated neoglucogenesis." (PMID 36836124, 2023). "The univariate analysis results showed that ten variables (T stage, N stage, M stage, pathologic stage, primary therapy outcome, age, residual tumor, CEA level, lymphatic invasion, and GCG expression) were statistically significantly related to the overall survival of COADREAD patients." (PMID 35340411, 2022). "The tumor cells were positive for at least one of pan-neuroendocrine markers including chromogranin, synaptophysin, neuron-specific enolase, CD56, and glucagon." (PMID 27956948, 2009). "The incidence of pNETs is rising in the western world, and these tumours are divided into functioning and non-functioning types, ranging from indolent to aggressive, depending on histology and the production of active hormones, including glucagon." (PMID 40649254, 2025). "The impact of systemic metabolism and diet on tumour evolution is still not fully comprehended, necessitating new experiments exploring the influence of systemic metabolic controllers such as insulin and glucagon." (PMID 40649254, 2025). "Also, the functional character of the tumor was analyzed, with the tumor cells being positive for insulin and negative for glucagon." (PMID 39941267, 2025).
tumor (continued). "Similarly, AL did not change tumor growth or angiogenesis, but reversed the glucagon produced by a synergistic effect on the inhibition of tumor angiogenesis, thus recovering tumor growth or vessels." (PMID 38072640, 2024). "Therefore, the glucagon‐induced antiangiogenic effect did not surpass the threshold of tumor inhibition." (PMID 38072640, 2024). "Similarly, decreased perfusion and increased extravasation of tumor vessels were detected in HFD tumors, similar to the exogenous glucagon treatment, indicating that elevated endogenous glucagon levels might contribute to the antiangiogenic effect." (PMID 38072640, 2024). "Nevertheless, these results indicate that glucagon may inhibit tumor angiogenesis rather than promote vessel growth." (PMID 38072640, 2024). "As expected, glucagon overexpression significantly reduced tumor growth when combined with 5‐FU treatment, although overexpressed glucagon alone did not induce significant tumor blockade." (PMID 38072640, 2024). "Interestingly, glucagon was highly expressed in majority of the normal tissue samples (92.7%) but not in tumor tissues (68.3%)." (PMID 38072640, 2024). "Furthermore, the potential of GCG modulation, GLP-1 receptor agonists, and immune-checkpoint inhibitor therapy in context of GCG expression of COADREAD can be investigated in a precision medicine approach to identify tumor subtypes and optimal therapies." (PMID 35340411, 2022). "Metastatic tumor masses along with the production of peptide hormones, such as gastrin, somatostatin, insulin, glucagon, or vaso inhibitory peptide (VIP) by tumor cells, may lead to severe symptoms and complications, such as diarrhoea, gastric ulcers, flush, diabetes, or hypoglycaemia." (PMID 31527438, 2019). "Tumor cells were positive for chromogranin A and glucagon, while insulin staining was negative." (PMID 27769070, 2016). "However, we saw that there was no glucagon or somatostatin staining of tumor cells in PDICs, indicating that PDICs lack expression of all pancreatic neuroendocrine cell type-specific markers." (PMID 23691228, 2013). "The administration of high glucagon doses constantly elevates glucose levels favoring the Warburg effect in the tumor microenvironment, leading to the rapid proliferation of tumor tissue, including endothelial cells, but may not affect VEGF signaling, as direct evidence was missing in that report." (PMID 38072640, 2024). "Furthermore, macrophages and stromal cells significantly decreased after glucagon treatment (data not shown), indicating changes in the tumor microenvironment, which may also contribute to tumor inhibition." (PMID 38072640, 2024). "Tumours are termed functional if they are associated with secretion of specific hormones, including insulin, glucagon and VIP hormone, with some causing symptoms such as facial flushing, diarrhoea, while nonfunctional tumours may show no overt signs of hormone-associated disease secretion." (PMID 36362433, 2022). "Insulin-like growth factor 2, insulin and glucagon are not involved in GSDME-SG-mediated tumour cell death in vitro; therefore we speculated that exocrine enzymes are involved in GSDME-deficient tumour cell death." (PMID 35292781, 2022). "Nonetheless, an analysis of metastatic versus non-metastatic COAD tissue revealed that EEC-related genes (GCG, PYY, CHGA, NEUROD1) were consistently downregulated in both tumor and normal tissue and between metastatic and normal tissue." (PMID 41303610, 2025). "In contrast, amylase, insulin, glucagon, and CK19 expression was largely absent in neoplasm in the pancreas of Pdx-1CreLKB1L/L mice that received the vehicle (DMSO)." (PMID 33924999, 2021). "Immunohistyochemically, tumor cells were positive for cytokeratin, synaptophysin, neuron-specific enolase, and CD56; they were negative for chromogranin, gastrin, glucagon, somatostatin, pancreatic polypeptide, and vasoactive intestinal polypeptide." (PMID 27990210, 2009).
tumor (continued). "As glucagon alone did not significantly inhibit tumor growth, we hypothesized that the improved survival of patients with CRC might be due to the combined effect of glucagon with other anticancer treatments." (PMID 38072640, 2024). "Tumours not expressing an abundance of SSTR-2 over SSTR-5 subtypes may have reduced response to these agents and may, in fact, experience preferential suppression of glucagon over insulin, leading to hypoglycaemia." (PMID 40697399, 2025). "Our data show a signaling cascade from extracellular glucagon to nuclear CREB in SNU398 GCGR cells, yet this fails to effectively induce gluconeogenic gene transcription, which we hypothesized would antagonize glycolysis to reduce tumor growth." (PMID 35123542, 2022). "Most tumor cells of the neuroendocrine component were immunoreactive for CAM.5.2, cytokeratin (CK) 7, CK AE1/AE3, synaptophysin, chromogranin A, parathormone, GATA3, and parafibromin, whilst they were negative for thyroglobulin, TTF1, calcitonin, glucagon, and S100." (PMID 32506375, 2021).
cardiovascular disease (40 papers, 2015 to 2026). "By inhibiting SGLT1, Sotagliflozin reduces glucose entry into the bloodstream, contributing to better long-term control of 2H-PPG, lower glucagon production, and a decreased risk of cardiovascular disease." (PMID 40529829, 2025).
infection (39 papers, 2010 to 2025). The state of being infected such as from the introduction of a foreign agent such as serum, vaccine, antigenic substance or organism. "GLP-1 RAs enhance insulin secretion and suppress glucagon, potentially reducing infection risk and subsequent revision." (PMID 41362522, 2025). "Infection and postoperative status stimulate the secretion of glucagon, cortisol, and catecholamines, thereby promoting insulin resistance, lipolysis, and ketogenesis despite normal blood glucose levels." (PMID 40502910, 2025). "The energy metabolism pathways identified in the PSRs, including Apelin, Phospholipase D, and Glucagon signaling pathways, suggest that modulation of energy homeostasis is crucial for host survival during infection." (PMID 40548231, 2025). "The glucagon pathway operates downstream of the insulin signaling pathway, which plays a central role in metabolic regulation during infection and inflammation." (PMID 39769543, 2024). "The EtOH-treatment produced a significant re-localization of glucagon toward the cytoplasm, whereas the infection in groups 3 and 4, significantly diminished the amount of this protein in pancreatic tissue." (PMID 39030443, 2024). "More importantly, treatment with either glucagon or Forskolin further augmented hepatic glucose production upon PIMT wild-type infection." (PMID 36866247, 2023). "Post 48h of infections, cells were treated with either glucagon or Forskolin, and hepatic glucose output was evaluated." (PMID 36866247, 2023). "After 48h of infection, cells were treated with either glucagon, Forskolin, insulin, or metformin and were subjected to glucose output assay." (PMID 36866247, 2023). "The differentially expressed proteins post-infection include Akap1, Prkaca, Prkab2, Acaca, Acacb, Aka1, Abcf1, Synj1, Braf, Vcl, and Fhod3, which involve insulin receptor signal, glucagon signal pathway, AMPK signal pathway, and Hippo signal pathway." (PMID 35313969, 2022). "To evaluate how glucagon inhibits the migration of mice neutrophil, we explored the molecular mechanisms that allow the recruitment of neutrophils to the site of infection." (PMID 34295325, 2021). "Upon infection, insulin transcript levels were reduced with a concomitant increase in alpha cell markers such as GCG, SMARCA1, RGS4, KLHL41, RFX6, TM4S4 and acinar cell markers such as PRSS1, PRSS2, SPINK1, CPB1, CPA1, CPA2, OLFM4." (PMID 34561952, 2021). "Remarkably, the ectopic expression of Pdx-1, Ngn-3 and Maf-A in hMSCs, combined with infection with HAdV.EF1α.DsRed.F50, increased glucagon gene expression up to 100-fold." (PMID 23110179, 2012). "From bioinformatic analysis, we identified three significant genes (GCG, APOA1, and IGFBP1) associated with the infection of H. pylori, and the survival nomogram based on the H. pylori-related genes exhibited good predictive power for survival outcome among GC subjects." (PMID 37846989, 2023). "Using a human pluripotent stem cell (hPSC)‐based model, following infection with SARS‐CoV‐2, the hPSC‐derived pancreatic endocrine cells showed a substantial proportion of spike protein‐positive SARS‐S+ INS+ and SARS‐S+ GCG+ cells." (PMID 34561952, 2021). "Infection of mouse primary hepatocytes with AdshTAZ reduced both TAZ mRNA expression and protein level and markedly increased the glucagon and dexamethasone (Dex)-induced mRNA expression of Pck1 and G6pc." (PMID 34622775, 2021). "A complex interplay between fever, seizure, and infection as combined stressors, triggering a cumulative, synergic interaction between proinflammatory cytokines and stress-related hormones (interleukins, growth hormone, insulin, glucagon) could offer a potential explanation." (PMID 32120784, 2020). "Conversely, the infection of mouse primary hepatocytes with AdTAZ increased TAZ protein levels threefold compared with infection with control AdGFP and substantially inhibited the glucagon and Dex-induced mRNA expression of Pck1 and G6pc." (PMID 34622775, 2021).
infection (continued). "Insulin, proinsulin, C-peptide, and glucagon concentrations of the orally- and i.c.-infected animals also remained stable during the infection period and were similar to the control group (data not shown)." (PMID 25090610, 2014). "Notably, the role of glucagon signalling and starch and sucrose metabolism in infection has not been reported." (PMID 35693845, 2022).
kidney disease (19 papers, 2018 to 2026). "In addition glucagon levels may be dependent on intact renal function (hyperglucagonemia in patients with renal disease may be composed of not only 1–29 glucagon but also considerable amount of 1–61)." (PMID 31284506, 2019).
kidney (6 papers, 2020 to 2025). "The results showed a significant decrease in the prevalence of non-alcoholic fatty liver across the tertiles for both fasting and postprandial glucagon to insulin ratios." (PMID 37762748, 2023). "Insulin and glucagon regulate lipolysis and we previously showed that serum glucagon is elevated and insulin signaling is dampened in late-stage lung TB mice, preventing insulin from exerting its anti-lipolytic effect." (PMID 36277179, 2022). "Therefore, reduced glucose-induced insulin secretion and reduced glucagon suppression may contribute to PTDM in kidney transplant recipients." (PMID 38397919, 2024).
colon polyps (4 papers, 2018 to 2024). "However, a positive history of colon polyps was significantly higher in the high GCG expression group." (PMID 35340411, 2022).
gastrointestinal disorders (4 papers, 2023 to 2024). "The most frequent gastrointestinal disorder was vomiting, a common side effect of glucagon treatment." (PMID 37930757, 2024).
neurological diseases (4 papers, 2022 to 2024). "These benefits include weight loss, liver enzymes and biomarkers improvements, optimal glucose homeostasis due to insulin and glucagon in the pancreas, less incidence of cardiopulmonary-related and neurological diseases, cardioprotective effects, and reductions in blood pressure." (PMID 36819350, 2023).
adenocarcinoma (3 papers, 2021 to 2024). A common cancer characterized by the presence of malignant glandular cells. "Cells of the adenocarcinoma component were CAM.5.2, CK7, CK AE1/AE3, and GATA-3 positive and negative for synaptophysin, chromogranin A, parathormone, parafibromin, thyroglobulin, TTF1, calcitonin, glucagon, S100, PGP-9 and Bcl-2." (PMID 32506375, 2021).
neurodegenerative disease (3 papers, 2017 to 2024). A disorder of the central nervous system characterized by gradual and progressive loss of neural tissue and neurologic function. "Pathway enriched by KEGG were mainly related to RNAs with citrate cycle, glucagon and metabolic pathway, HIF-signaling pathway, retrograde endocannabinoid signaling, and several ageing related degenerative diseases." (PMID 37007946, 2023).
peripheral neuropathy (2 papers, 2021 to 2024). A disorder affecting the peripheral nervous system. "We previously reported that deficiency of glucagon gene-derived peptides, including GLP-1 and glucagon, caused peripheral neuropathy in mice." (PMID 33672050, 2021).
bacterial infections (1 paper, 2025). "A previous study has described unusually high concentrations of glucagon in the plasma of patients with various bacterial infections." (PMID 39888969, 2025).
GCG also shares sentences with these, for which no sentence is quoted: chronic kidney disease (32 papers); Parkinson disease (25); inflammatory bowel disease (21); endothelial dysfunction (13); psoriasis (12); osteoporosis (10); acute pancreatitis (8); diabetic retinopathy (7); endotoxemia (7); atrial fibrillation (6); anemia (5); chronic pancreatitis (5); dementia (5); inflammation (5); obstructive sleep apnea (5); acute graft versus host disease (4); acute kidney injury (4); acute myocardial infarction (4); cognitive decline (4); deep vein thrombosis (4); enteritis (4); gastrointestinal disease (4); irritable bowel syndrome (4); memory impairment (4); pulmonary hypertension (4); retinopathy (4); rheumatoid arthritis (4); ulcerative colitis (4); alcohol use disorder (3); Atrophy (3).
A further 238 diseases each share a sentence with GCG in 3 papers or fewer.